EPCAM (epithelial cell adhesion molecule)
Diseases named in the same sentence as EPCAM in open-access papers (continued):
Sharing a sentence is not in itself a finding about the gene and the disease.
tumor (continued). "The epithelial cell adhesion molecule (EpCAM) is highly expressed in tumors and it helps regulate the epithelial-mesenchymal transition, giving it a key role in the invasion and metastasis of tumor cells; this molecule can bind specifically to EpCAM aptamer on NPs." (PMID 36059964, 2022). "Importantly enough, EpCAM has been widely recognised as being expressed in circulating tumour cells (CTCs), which are highly suspected to be enriched in a CSC function and activity, allowing the survival of cancer cells in anoikis-independent conditions." (PMID 35326385, 2022). "Interestingly, the tumour cells (identified by EpCAM expression) expressed very high levels of the mesenchymal CRC markers ZEB1 and HTR2B, which can be used to distinguish mesenchymal-like CRC (now commonly referred to as CMS4) from non-mesenchymal CRC." (PMID 35296803, 2022). "In vivo experiments showed that EpCAM blockade could enhance macrophage infiltration to efficiently eliminate tumor cells." (PMID 36369033, 2022). "EpCAM-positive CSCs contribute to tumor establishment and invasiveness." (PMID 35204240, 2022). "As EpCam+ tumor cells expressed G‐CSF in GC tumors, we isolated EpCam+ cells from tumor and non‐tumor tissues of autologous GC patients, and cultured them to obtain tumor cell culture supernatants and non‐tumor cell culture supernatants, then stimulated neutrophils with these supernatants." (PMID 34957697, 2022). "Moreover, in agreement with previous reports, coculture with TASCs resulted in increased proliferation of EpCAM+ tumor cells, mediated by IL-6, and higher invasive capacity." (PMID 35454931, 2022). "That might be due to EpCAM mAb with low dissociation constant to EpCAM (kdis = 10−7 s−1) could specifically target tumor cells and then lead to a more prolonged and robust ADCC activity in this model." (PMID 35281893, 2022). "Using flow cytometry, we identified tumors as mCD45-, hCD45-, EpCAM+ in the tumor cell suspensions and quantified the mean fluorescence intensity (MFI) of HLAs on the tumors as well as the mCD45+ and hCD45+ cells in the TILs, as negative and positive controls, respectively." (PMID 36419897, 2022). "These cells expressed the tumour marker EpCam and macrophage markers CD163, CD68, CSFR1, and CD66b." (PMID 35563449, 2022). "Moreover, these multiple nanoparticles exhibited high affinity for EpCAM+ tumor cells and low toxicity to healthy cells, resulting in enhanced immunotherapeutic efficacy." (PMID 36369033, 2022). "Moreover, the detection of EpCAM-positive circulating tumor cells is strongly correlated with the clinical outcome and OS in patients with HCC." (PMID 35070966, 2021). "Notwithstanding EpCAM/CK staining, total CTCs should also be stained for epithelial-mesenchymal transition markers because “Circulating” tumour cells are evading tumour cells originated from primary tumour tissue." (PMID 33462311, 2021). "The high amount and the internalization ability of miR-429 in HCC cells, specifically in epithelial cell adhesion molecule (EPCAM) + T-ICs, contribute to promoting and developing tumor features such as self-renewal, tumorigenicity, malignant proliferation, chemoresistance, and progression." (PMID 34207985, 2021). "Our present results revealed that IL-11+, EpCAM+, and E-cadherin+ epithelial cells might be tumor cells themselves." (PMID 33863879, 2021). "The primary objective of this upcoming REMOVE study is to demonstrate that the Catuvab device utilized during IBS procedures (including centrifugation step and leukocyte depletion filter) depletes EpCAM-positive tumor cells effectively in autologous blood retransfusion." (PMID 34715784, 2021).
tumor (continued). "This heterogenous expression of EpCAM in NSCLC cells may be related to the EMT process whereby epithelial tumour cells often undergo epithelial-mesenchymal transition (EMT)." (PMID 33550205, 2021). "But through which complex regulatory mechanisms does vinculin affects MET, activates NK cell toxicity and causes tumor cell immune escape, and through in vivo experiments, we confirmed that VCL can affect EMT and tumor immunity by regulating the expression of EPCAM." (PMID 33535187, 2021). "In 8 out of 11 patients analyzed, EpCAM expression was assessed in the primary tumor too." (PMID 34063272, 2021). "The prepared anti-EpCAM/AuNPs electrode was specific for tumor cell anchoring." (PMID 34858966, 2021). "Similarly, ovarian-cancer-derived sEVs express CD24 and EpCAM, which are tumor-exclusive markers and therefore can differentiate between cancerous and non-cancerous lesions." (PMID 34571921, 2021). "The anti-tumor effect of EpCAM-targeting treatment with Ec1-LoPE alone or in combination with the HER2-targeting mAb trastuzumab was evaluated in BALB/c nu/nu mice bearing EpCAM- and HER2-expressing SKOV3 xenografts." (PMID 34439094, 2021). "EpCAM induces cell plasticity within epithelial tissues by weakening cadherin-mediated cell adhesion, which can promote cell proliferation and motility during tumor progression." (PMID 34671766, 2021). "In other words, EpCAM+ CTCs are strongly correlated with tumor aggressiveness and could assist in the adequate stratification of HCC patients for optimal therapy and in predicting their response to treatment." (PMID 34884878, 2021). "Here, we found that the AD population includes mainly CD90+ cells with highly proliferative rates in vitro but no tumorigenic potential in vivo, whereas the NAD population contains principally tumor cell spheroids (EpCAM+/CD24+) with low proliferative potential in vitro." (PMID 34060699, 2021). "Anti-EpCAM antibody also captures epithelial non-tumour cells in the blood." (PMID 34188122, 2021). "The GC tumor cells were counted as the EpCAM-positive epithelial cells." (PMID 34336697, 2021). "EpCAM is a target of molecular therapies and plays a prominent role in tumor biology." (PMID 34209658, 2021). "On the other hand, the liver-abundant miR-192-5p is a tumor suppressor (TS) miRNA strictly associated with cancer stem cells isolated from HCC specimens, resulting in downregulated EpCAM+, CD44+, CD90+, CD133+, and CD24+ CSC-enriched populations compared to negative ones." (PMID 34572776, 2021). "However, PD-L1 expression on CD31+ endothelial cells and EpCAM+ tumor cells remained unchanged, while there was a trend of decrease in CD45+ cells." (PMID 34673569, 2021). "In this study, we demonstrated the feasibility of in situ immobilization of human anti-EpCAM antibodies onto the interior surface of commercially available hollow hemodialysis fibers for the selective capture of circulating tumor cells while maintaining its hemodialysis performance." (PMID 34443432, 2021). "At the start of a new treatment course, significantly fewer EpCAM-positive samples were observed, which, at first glance, seems contradictory because one might suggest a higher tumor load at progression." (PMID 34834576, 2021). "We assumed a tumor tissue containing a cell density of 2.9 × 108 cells/mL, representing a tumor with a high cellularity, and a receptor density of 5.4 × 105 receptors/cell, which we previously determined for EpCAM on MCF-7 cells." (PMID 33921165, 2021). "Solitomab-treated animals had decreased tumor burden over time and exhibited a significant increase in ZipGFP-Casp3–labeled apoptotic cells starting at 24 h after therapy compared with control EpCAM antibody–treated fish (P < 0.01, Student’s test)." (PMID 34415995, 2021). "Furthermore, the only FDA-approved technology for circulating tumor cell isolation (in colon, breast and prostate tumors), with prognostic potential, is based on the selection of EpCAM-positive cells." (PMID 34829955, 2021).
tumor (continued). "EpCAM expression in tumor tissue was found in only 7% (7/109) of these HCC patients." (PMID 33915518, 2021). "Additionally, instead of p16/EpCAM, pan-cytokeratin (pCK) was used for identification of tumor cell nests to improve versatility." (PMID 34777389, 2021). "Elevated numbers of ZipGFP-Casp3+ cells were observed by 24 h after treatment, preceding the overall reduction in tumor cells that was observed at 4 and 7 d after treatment with EpCAM/CD3 solitomab, suggesting that BiTE-induced cell killing required >24 h to reach maximal efficiency." (PMID 34415995, 2021). "While some background EpCAM staining was detected in non-tumor-bearing (PyMT−) bone marrow, a significant decrease in the number of EpCAM+ cells was detected in the bone marrow from Hif1α−/− PyMT+ mice compared to Hif1αf/f PyMT+ mice when normalized to total tumor weight at end point." (PMID 34556788, 2021). "The epithelial cell adhesion molecule (EpCAM) is a transmembrane glycoprotein that has a basal-level expression on non-pathologic epithelial cells and intense overexpression in many epithelial tumors, on cancer stem cells, and on circulating tumor cells." (PMID 34439094, 2021). "Moreover, the decreased protein level of EpCAM was confirmed in mouse metastasis tumor tissues derived from SiHa-Slug cells by western blot (p < 0.05)." (PMID 33691694, 2021). "In human carcinomas, EpCAM is commonly elevated in various primary tumor types." (PMID 33691694, 2021). "The false negativity may be due to an epithelial-mesenchymal transition (EMT) of tumor cells during progression; like in tissue specimens, CTCs may downregulate the epithelial markers (such as EpCAM), upregulating mesenchymal proteins." (PMID 34945784, 2021). "All informative tumor samples were positive for EpCAM staining." (PMID 34834440, 2021). "The CD11c+ APCs were mainly found in the EpCAM- tumor stroma alongside CD8+ TILs." (PMID 34680397, 2021). "Furthermore, we show that CEA, EpCAM, and αvβ6 expression is significantly lower in the pCR tumor bed compared with adjacent pre-existent mucosa." (PMID 33799475, 2021). "The molecular surface markers CD44 and EpCAM were determined to identify whether it was a tumor stem cell." (PMID 34239355, 2021). "In order to better characterize these two cell populations, an additional FACs panel including a tumor marker (EpCAM), stem cell markers (CD44, CD24, and CD133) and mesenchymal‐like and mesothelial cell markers (CD90, podoplanin and mesothelin) was established." (PMID 34060699, 2021). "EpCAM+ tumour cells that co-express CD73 were also found to express CD39 and PD-L1." (PMID 34740105, 2021). "The combined use of a Tim-3 inhibitor and MT110 (anti-CD3× anti-EpCAM) could enhance the anti-tumor effect of the adoptively transfused γδ T cells, which have clinical implications for the design of new anti-tumor regimens." (PMID 34504800, 2021). "Alternatively, a clear association between the epithelial cell adhesion molecule (EpCAM)-positive CTC-fraction and circulating tumor DNA (ctDNA) for promotor methylation of the transcriptional regulator SOX17, but not for CST6, was found for both patients with early and metastatic breast cancer." (PMID 33919854, 2021). "In this study, we report on the in situ modification technology of commercially available hemodialysis membranes to selectively capture circulating tumor cells from the blood stream by means of immobilized anti-human EpCAM antibodies at the interior surface of the fibers." (PMID 34443432, 2021). "EpCAM staining was found in 50% of cells in both non-tumour and tumour tissue." (PMID 33906633, 2021). "Given that most tumour cells are of epithelial origin, many methods of detection and isolation of CTCs from patient blood samples involve the use of epithelial markers such as pan cytokeratin (panCK) and epithelial cell adhesion molecule (EpCAM)." (PMID 33789677, 2021). "Results from NGS testing revealed a possible EPCAM copy-number deletion in the tumor tissue." (PMID 33747906, 2021).
tumor (continued). "VCL can affect EMT and tumor immunity by regulating EPCAM gene expression." (PMID 33535187, 2021). "Thus, in the current study, TSR was assessed automatically in digitalized EpCAM-stained tumors and correlated with the clinical outcome and molecular phenotype of tumor cells in PCa patients." (PMID 34834440, 2021). "Moreover, limited CD73 expression was observed in EpCAM+ tumor cells in majority of the specimens, except for a few CAF-rich specimens where CD73hi signal was detected in the lumina." (PMID 31980601, 2020). "Gross liver anatomy and H&E staining confirmed HCC tumor growth in the EpCAM-High group of animals." (PMID 32547703, 2020). "In the tumor cells, moderate or strong expression of EpCAM was detected in 11 of 13 cases by IHC." (PMID 33276608, 2020). "While this applies to most carcinoma cells, metastatic outspread is often associated with the transition of epithelial-like tumor cells into a more mesenchymal state (epithelial to mesenchymal transition, EMT), indicated by loss or downregulation of EpCAM expression." (PMID 32069934, 2020). "Poor prognostic values of EpCAM+ tumor cells or CTCs in cancer patients were described elsewhere." (PMID 32599893, 2020). "Female athymic nude mice were intraperitoneally injected with luciferase-expressing OCC1 or SK-OV3 cells and administration of Control and EpCAM-siPKCι aptamer at 200nmole/mouse began as soon as tumor was detected (about 1 week after intraperitoneal injection of 107 cells/animal)." (PMID 32820156, 2020). "Here, EpCAM has dual potential as a quantifier of systemic tumor cells in the frame of liquid biopsies and as a potential target for adjuvant therapy of residual tumor cells with specific biologicals." (PMID 32507912, 2020). "Observed EpCAM mediated faster tumor development and growth may be due to higher number of CSCs present in this cell population as well." (PMID 33490064, 2020). "In this context, tumour rigidity could become a limiting factor, which could be alleviated by EpCAM’s “plasticizing” action." (PMID 32961790, 2020). "Initially, the patient with stemness gene amplifications had a high concentration of EpCam+CD44+CD24– tumor stem cells – more than 50%, while patient Ti41749/17 had a level slightly above 30% and a two-fold higher concentration of EpCam+CD44hiCD24– cells (37% compared with 18%)." (PMID 32523653, 2020). "This study has some limitations; confirmation of EpCAM positivity by immunocytochemistry was needed to give more precise information, also follow up of EpCAM positive cases for long durations was needed to detect the impact of EpCAM on the patients’ survival and tumor metastasis." (PMID 32212818, 2020). "Therapies against EpCAM+ CTCs could target not only cancer cells in the primary tumor, but also CTCs as the drivers of cancer dissemination." (PMID 32764280, 2020). "Tumor-containing ovaries stained intensely and extensively for EpCAM by immunohistochemistry." (PMID 31923221, 2020). "Positive EpCAM expression was demonstrated by IHC in both primary tumor and metastatic lesions." (PMID 32041116, 2020). "In addition, the tumour-initiating cells are also found to be enriched with EpCAM, thus classifying EpCAM as one of the cancer stem cell markers in several cancer types." (PMID 32046162, 2020). "As such, CTC detection based only on EpCAM (EpCAM+) might have missed a substantial number of tumor cells." (PMID 31947893, 2020). "But recent (pre)clinical studies indicate that a ratio of at least 2 in favor of the tumor might suffice for other tumor targets like EpCAM." (PMID 32751634, 2020). "The PDT effect of the DARPin-IRDye 700DX conjugates was restricted to EpCAM-expressing tumor cells." (PMID 32630661, 2020). "EpCAM has received considerable attention in the liquid biopsy field because it is used in the CellSearch® system (Menarini-Silicon Biosystems, Italy, 2020, and Janssen Diagnostics Raritan, NJ, USA, 2004) to detect circulating tumor cells (CTCs)." (PMID 32764280, 2020).